MEPE (matrix extracellular phosphoglycoprotein)
Description:
Promotes renal phosphate excretion and inhibits intestinal phosphate absorption. Promotes bone mineralization by osteoblasts and cartilage mineralization by chondrocytes. Regulates the mineralization of the extracellular matrix of the craniofacial complex, such as teeth, bone and cartilage (By similarity). Promotes dental pulp stem cell proliferation and differentiation.
Synonyms: OF45
Tractability: Antibody: UniProt places it where antibodies can reach, with high confidence; its Gene Ontology location is reachable by antibodies, with high confidence; UniProt predicts a signal peptide or a membrane-spanning region.
Gene: Protein-coding gene on chromosome 4 (87,821,398 to 87,846,814, forward strand). Ensembl gene ENSG00000152595.
Subcellular location: Secreted, extracellular space, extracellular matrix; Secreted
Pathways (Reactome):
Metabolism of proteins: Post-translational protein phosphorylation; Regulation of Insulin-like Growth Factor (IGF) transport and uptake by Insulin-like Growth Factor Binding Proteins (IGFBPs)
Gene Ontology:
Molecular function: protein binding; extracellular matrix protein binding; extracellular matrix structural constituent
Biological process: biomineral tissue development; skeletal system development
Cellular component: extracellular region; endoplasmic reticulum lumen; extracellular matrix; non-collagenous component of interstitial matrix
Genetic constraint (gnomAD): Loss-of-function variants: 7 observed, 6.23 expected, observed/expected ratio (o/e) 1.12, 90% interval 0.63 to 1.83. That is too few expected variants to judge how well the gene tolerates losing a copy. Missense variants: 618 observed, 656.17 expected, observed/expected ratio (o/e) 0.94, 90% interval 0.88 to 1.01. Synonymous variants: 214 observed, 224.45 expected, observed/expected ratio (o/e) 0.95, 90% interval 0.85 to 1.07.
Homologues: Orthologues: chimpanzee MEPE (98% identical), macaque MEPE (92% identical), dog MEPE (71% identical), pig MEPE (68% identical), rabbit MEPE (63% identical), mouse Mepe (44% identical), rat Mepe (42% identical).
Diseases named in the same sentence as MEPE in open-access papers:
MEPE is named in the same sentence as 24 diseases in open-access papers, as found by Europe PMC text mining. Sharing a sentence is not in itself a finding about the gene and the disease. The quoted sentences say what the papers report.
hypophosphatemia (5 papers, 2014 to 2023). Lower than normal levels of phosphates in the circulating blood. "Overexpression of MEPE and SFRP-4 can lead to abnormal renal phosphate metabolism and bone mineralization, causing hypophosphatemia and increased renal phosphate excretion." (PMID 38116308, 2023). "A study also reported that MEPE mRNA expression was up-regulated in bone and osteoblasts derived from hypophosphatemia mice." (PMID 34380559, 2021).
osteoporosis (4 papers, 2011 to 2026). A condition of reduced bone mass, with decreased cortical thickness and a decrease in the number and size of the trabeculae of cancellous bone (but normal chemical composition), resulting in increased fracture incidence. "MEPE p.Lys70IlefsTer26 carriers show higher risk for multiple types of fractures as well as osteoporosis with odds ratios (OR) ranging between 1.35 and 2.06." (PMID 33097703, 2020). "Therefore, MEPE can be a possible therapeutic target to prevent osteoclastogenesis in diseases like osteoporosis and osteomalacia." (PMID 36834981, 2023).
X-linked hypophosphatemic rickets (3 papers, 2008 to 2013). "Studies into rare genetic disorders, such as X-linked hypophosphatemic rickets (XLH), have identified a family of proteins, FGF23, PHEX, and MEPE which act through a bone-kidney axis to modulate phosphate homeostasis and thus bone mineralization indirectly." (PMID 22766095, 2012).
autosomal dominant hypophosphatemic rickets (2 papers, 2008 to 2017). Autosomal dominant hypophosphatemic rickets (ADHR) is a hereditary renal phosphate-wasting disorder characterized by hypophosphatemia, rickets and/or osteomalacia. "Presence of excess of FGF23 and matrix extracellular phosphoglycoprotein (MEPE) in oncogenic osteomalacia indicates similarities with genetically inherited rickets such as X-linked and autosomal dominant hypophosphatemic rickets." (PMID 28300755, 2017).
dystocia (2 papers, 2013 to 2025). Slow or difficult obstetric labor or childbirth. "IBSP and MEPE were identified as possible candidates for protein and fat percentage in Israeli Holstein, but have also been associated with bone formation in humans and declared as candidate genes for dystocia and stillbirth in Norwegian Red cattle." (PMID 24359457, 2013).
osteosarcoma (2 papers, 2022 to 2023). A usually aggressive malignant bone-forming mesenchymal neoplasm, predominantly affecting adolescents and young adults. "Co-expression network analysis has revealed MEPE as a dysregulated gene in human osteosarcoma." (PMID 35456486, 2022). "Expression of osteocyte markers (i.e., DMP1, MEPE, or PHEX) has been observed in the osteoblastic subtype of human osteosarcoma, indicating that osteocytes may potentially serve as progenitors for osteosarcoma cells." (PMID 37174109, 2023).
otosclerosis (2 papers, 2022 to 2023). Formation of spongy bone in the labyrinth capsule which can progress toward the stapes (stapedial fixation) or anteriorly toward the cochlea leading to conductive, sensorineural, or mixed hearing loss. "The most recent GWAS was performed as a meta-analysis from three different biobanks: FinnGen, EstBB and UKBB, resulting in the identification of 18 loci associated with otosclerosis, including genes that were previously associated with otosclerosis, e.g., RELN, TGFβ1 and MEPE." (PMID 36498562, 2022). "Furthermore, MEPE, a classic FAM20C target, is involved in otosclerosis, affecting the bone remodeling of the otic capsule." (PMID 37240249, 2023).
dementia (1 paper, 2026). Loss of intellectual abilities interfering with an individual's social and occupational functions. "Two proteins, sFRP4 and MEPE, were linked to reduced Brain Age, with sFRP4 also being protective against dementia." (PMID 41555457, 2026).
hypophosphatemic rickets (1 paper, 2013). Rickets due to low serum phosphate concentrations, the cause of which can be nutritional or genetic. "Among the SIBLING proteins, MEPE (matrix extracellular phosphoglycoprotein) has been shown to be involved in pathologic processes associated with hypophosphatemic rickets." (PMID 23451077, 2013).
mesenchymal tumors (1 paper, 2021). "In TIR and TIO, small mesenchymal tumors secrete FGF23 and/or other phosphatonins such as matrix extracellular phosphoglycoprotein (MEPE)." (PMID 33815294, 2021).
osteogenesis imperfecta (1 paper, 2023). Osteogenesis imperfecta (OI) comprises a heterogeneous group of genetic disorders characterized by increased bone fragility, low bone mass, and susceptibility to bone fractures with variable severity. "In osteogenesis imperfecta, similarly to carriers of truncating MEPE variants, increased bone turnover in the middle ear could occur in association with general skeletal fragility." (PMID 36653343, 2023).
Paget disease (1 paper, 2023). A malignant neoplasm composed of large cells with large nuclei, prominent nucleoli, and abundant pale cytoplasm (Paget cells). "Moreover, MEPE and ERK together can be used to prevent osteoclastogenesis and osteoblastogenesis in diseases like Paget disease." (PMID 36834981, 2023).
viral infections (1 paper, 2023). "For the first time, we have identified new CRS-related genes such as ADGRG7, probably reflecting cellular-adhesion elements, LACRT, IBSP, MEPE, and IFITM5, probable antimicrobial genes with a potential role in viral infections." (PMID 36982612, 2023).
tumour (3 papers, 2010 to 2024). "Expression of MEPE was 104 to 105 times higher in TIO-associated tumours than in control tumours." (PMID 38731904, 2024). "MEPE was first cloned and characterised in three tumours causing TIO." (PMID 38731904, 2024). "If these findings reflect the need to better define the appropriate dosing regimen and/or the expression (and secretion) by tumor cells of other phosphatonins (e.g., MEPE, FGF7, sFRP-4), it remains to be established." (PMID 37436671, 2023). "The aim of this study was to determine the role of human MEPE/OF45 (hMEPE/OF45 has ∼50% homology with rat MEPE/OF45 (rMEPE/OF45)) in affecting the sensitivity of human tumour cells to DNA damage." (PMID 20145617, 2010).
cancer (1 paper, 2019). A tumor composed of atypical neoplastic, often pleomorphic cells that invade other tissues. "Twelve genes were located in eight of the top-15 breakpoint regions, and six of these genes are associated with cancer (CACNA1B, IBSP, MEPE, NBEA, RELN and THSD7A)." (PMID 31249626, 2019).
MEPE also shares sentences with these, for which no sentence is quoted: gout (3 papers); genetic diseases (2); Stillbirth (2); cataract (1); hyperuricemia (1); infection (1); osteomalacia (1); ovarian carcinoma (1); rickets (1).